CRP (C-reactive protein)
Diseases named in the same sentence as CRP in open-access papers (continued):
Sharing a sentence is not in itself a finding about the gene and the disease.
cardiovascular disease (continued). "Levels of GDF-15, CRP and Cystatin C were determined in three repeated measurements collected 5 years apart in the DAN-MONICA (Danish-Multinational MONitoring of trends and determinants in Cardiovascular disease) cohort (participants at baseline n = 3785)." (PMID 29771963, 2018). "Recently, the neutrophil-to-lymphocyte ratio (NLR), platelet-lymphocyte ratio (PLR), and C-reactive protein-to-albumin ratio (CAR) have been suggested as useful and cost-effective prognostic biomarkers in various diseases, including malignant and cardiovascular diseases." (PMID 29293605, 2018). "Recent studies have suggested that neutrophil-to-lymphocyte ratio (NLR) and C-reactive protein-to-albumin ratio (CAR) are emerging markers of disease activity and prognosis in patients with chronic inflammatory diseases, cardiovascular diseases, or malignancies." (PMID 29293605, 2018). "After excluding participants with cardiovascular disease, IL-6 and CRP levels were still not found elevated in impaired cognitive function patients compared to healthy controls." (PMID 28798686, 2017). "There is strong evidence that IL-6 serum concentration increases with age and it is associated with an increased risk of cardiovascular disease (CVD) mortality, independent of CRP level." (PMID 26366318, 2015). "We investigated whether atorvastatin 10 mg daily lowered C-reactive protein (CRP) and whether the effects of atorvastatin on cardiovascular disease (CVD) varied by achieved levels of CRP and LDL-cholesterol." (PMID 25899452, 2015). "The Multinational Monitoring of Trends and Determinants in Cardiovascular Disease study discovered a higher CRP baseline in former smokers than nonsmokers 20 years after smoking cessation." (PMID 25105149, 2014). "C-reactive protein (CRP), which is an acute-phase protein, has been described as a non-specific biomarker of inflammation and risk factor for cardiovascular disease (CVD)." (PMID 24866016, 2014). "For men, CRP was primarily elevated among patients with no regular physical activity (aRR 1.5 (95% CI 1.1-1.9)), previous cardiovascular disease (aRR1.5 (95% CI 1.2-1.9) and other comorbidity." (PMID 25163828, 2014). "Within the limitations of this study, it may be concluded that the clinically successful non-surgical periodontal therapy tend to reduce concentration of circulating pro inflammatory cytokines (CRP, TNF-α), which could be important for cardiovascular disease." (PMID 24198887, 2013). "CRP is a nonspecific inflammatory biomarker that has been shown to be an important predictor of cardiovascular disease." (PMID 22518315, 2012). "Early initiation of statin treatment in normolipidemic subjects without cardiovascular disease and elevated C-reactive protein levels has a significant favorable impact on cardiovascular risk." (PMID 22364136, 2012). "In addition, we will also discuss the clinical evidence for the critical involvement of ROS production on the progress of cardiovascular disease (CVD), especially in the patient population with high levels of HDL cholesterol and C-reactive protein (CRP)." (PMID 22991685, 2012). "C-reactive protein (CRP) is a general marker of inflammation that reflects the summation of the pro-inflammatory and anti-inflammatory cytokines and has been shown to predict cardiovascular disease in many groups of adult patients." (PMID 22420715, 2012). "Specific examples of an SRM-multiplex quantitative assay platform dedicated to the cardiovascular disease area, screening Apo A1, Apo A4, Apo B, Apo CI, Apo CII, Apo CIII, Apo D, Apo E, Apo H, and CRP biomarkers used in daily diagnosis routines in clinical hospitals globally, are presented." (PMID 21884626, 2011). "This may be clinically important, not only for its impact on acute Gouty Arthritis and the risk of recurrent flares, but also because of the possible role of elevated CRP and SAA levels and IL-1β in the development of cardiovascular disease." (PMID 21439048, 2011).
cardiovascular disease (continued). "Previous research has demonstrated that although CRP is reliablyassociated with cardiovascular disease (CVD) outcomes, CRP does not appear to becausally involved in the development of CVD." (PMID 21602933, 2011). "Additionally, as we did not screen for other established CVD risk factors like microalbuminuria, homocysteinaemia and C reactive protein, the relative contributions of each of these to the burden of cardiovascular disease in our environment could not be determined." (PMID 20180977, 2010). "Although the exact mechanisms by which particles induce cardiovascular diseases are not known, studies suggest involvement of systemic acute phase responses, including C-reactive protein (CRP) and serum amyloid A (SAA) in humans." (PMID 19374780, 2009). "Circulating IL-6 concentrations also predict cardiovascular disease in the general population, independent of hs-CRP levels." (PMID 15899050, 2005). "The low incidence in cardiovascular disease despite the low level of HDL, high levels of CRP and reduction of LDL receptor expression lead to the conclusion that either these are not risk factors in these patients or that other risks factors – not yet identified – are considerably lower." (PMID 15705198, 2005). "Additionally, non-nutritional factors such as cardiovascular disease and other conditions of inflammatory origin, like infections, can also affect CRP levels." (PMID 40094974, 2025). "The 2 groups exhibited significant differences in terms of age, Cf-PWV, cardiovascular disease, peripheral arterial diastolic pressure, central arterial diastolic pressure, albumin, blood urea nitrogen, serum creatinine, LVEF, 25 hydroxyvitamin D3, C-reactive protein, and serum phosphorus." (PMID 39121296, 2024). "In addition, CRP has been widely used as a non-specific biomarker for inflammation and tissue damage, such as cardiovascular diseases, in clinical medicine." (PMID 38005386, 2023). "CRP is highly sensitive but not very specific for cardiovascular diseases." (PMID 37484982, 2023). "Indeed, CRP also targets neutrophils, platelets, or other tissue-resident CD32+ cell types that may be relevant to cardiovascular diseases (such as endothelial cells, cardiomyocytes, or fibroblasts that were not explored in our study)." (PMID 35203703, 2022). "Study participants had T2DM with no history of inflammatory diseases, cardiovascular diseases, medication and/or any health condition that might affect the inflammatory markers, interleukin 6 (IL-6) and C-reactive protein (CRP)." (PMID 34991564, 2022). "All categories of plasma vitamin C levels were associated with CRP levels of <1 mg/dL and mean RDW percentages of 12.9–13.0% which are currently considered low risk for cardiovascular disease, according to current AHA guidelines and not clinically recognized as relevant." (PMID 35334908, 2022). "In conclusion, our results show that both LDL-C and CRP are positively associated with the risk of MVE among patients with CKD, and that the association between LDL-C and cardiovascular disease is not significantly dependent on the severity of any underlying inflammatory response." (PMID 29146277, 2018). "It should be noted that the primary endpoints of the included studies were cardiovascular disease, LDL-cholesterol levels, HDL-cholesterol levels, or other outcomes such as serum triglyceride levels, apolipoprotein B, serum dehydroepiandrosterone sulfate levels, and C-reactive protein levels." (PMID 30425742, 2018). "The data consist of values of 4 clinical parameters (gender, age, race, BMI) along with 17 blood biomarkers and 53 SNPs all presumptively associated with cardiovascular disease risk in 166 non-diabetic post-MI patients having concurrently high levels of HDL-C and CRP." (PMID 27284570, 2016).
cardiovascular disease (continued). "Our data suggest that TNF-α and IL-6, but not CRP, are associated with the prevalence and severity of CKD, independent from established CKD risk factors, history of cardiovascular disease, and use of antihypertensive, antidiabetic, and lipid-lowering agents and aspirin." (PMID 26025192, 2015). "As shown in another Chinese study enrolling adult males with risk factors for cardiovascular diseases, the age-adjusted inverse association between OCN and CRP was observed in men with NGT and normal BMI but was not statistically significant after further adjusting for visceral fat area." (PMID 26578821, 2015). "Specifically, when cohort with only one condition was stratified into cardiovascular disease and non-cardiovascular morbidity cohorts, the levels of CRP were similar in those with and without cardiovascular disease: 0.369 ± 0.029 mg/dL vs. 0.399 ± 0.011 mg/dL (p = 0.33)." (PMID 25638154, 2015). "In our study, observed cross-cohort increase in the levels of C-reactive protein was especially striking when contrasted to the lack of difference in levels of CRP when patients with any cardiovascular disease were compared to the cohort with any non-cardiovascular morbidity." (PMID 25638154, 2015). "However, our findings are consistent with the prospect of sPLA2-IIa being a ‘chicken’ rather than just another ‘egg’ with respect to cardiovascular disease, very much in contrast to C-reactive protein." (PMID 21799821, 2011). "Furthermore, simulating a high CRP level (such as in the case of cardiovascular disease) under the normal healthy condition did not further increase the bacterial killing rate." (PMID 21283780, 2011). "In addition, it is now established that reduction plasmatic adiponectin and increased C-reactive protein (CRP) and plasminogen activator inhibitor-1 (PAI-1) levels play a role in the maintenance of an inflammatory state and in the development of cardiovascular disease." (PMID 20205861, 2010). "A possible explanation for our findings is that neutrophilic airway inflammation is associated with some systemic inflammation pathways, such as TNFα which is known to be involved in muscle inflammation, but not CRP which is an indicator of cardiovascular disease." (PMID 19480658, 2009). "In multivariable-adjusted Cox models, higher levels of KYN were associated with an increased risk of cardiovascular disease (HR 1.33; 95% CI: 1.19–1.49), while elevated KTR also conferred higher risk (HR 1.24; 95% CI: 1.14–1.35), independent of traditional risk factors and CRP levels." (PMID 40426950, 2025). "Among the patients with cardiovascular disease, the digital health intervention did not significantly affect systolic blood pressure, diastolic blood pressure, lipids, blood glucose level, glycosylated hemoglobin level, C-reactive protein, or smoking frequency." (PMID 34989681, 2022). "Secondly, this study was only designed to examine the hs‐CRP levels but not to other inflammatory biomarkers such as IL‐6 and tumor necrosis factor α, which have also been identified as stronger predictors of clinical events in patients with cardiovascular diseases." (PMID 32458487, 2020). "Incremental C-statistics were examined when hs-CRP and physical health metrics were added to the conventional FRS model: either handgrip strength or relative handgrip strength improved prediction of all-cause mortality in the whole sample and in subjects without prevalent cardiovascular diseases." (PMID 28079182, 2017). "In this study, anthropometric data from asymptomatic people without known cardiovascular disease demonstrated a significantly positive correlation between coronary calcium score and traditional anthropometrics, blood pressure, insulin resistance, and systemic inflammation marker in terms of hs-CRP." (PMID 22254139, 2011). "We did not evaluate high-sensitivity CRP, IL-1, IL-6, ST2, TNFα, or VEGF, all of which are considered inflammatory regulators in cardiovascular diseases." (PMID 35328412, 2022).
cardiovascular disease (continued). "Age, the prevalence of cardiovascular disease, Charlson comorbidity index, SARC-F, Kt/V, and C-reactive protein were higher among non-survival patients, while BMI, serum albumin, creatinine, phosphorus, and nPNA were higher among survival patients." (PMID 33142777, 2020). "There is evidence from large epidemiological studies that levels of CRP, IL-6, and TNF-α are independent predictors of future cardiovascular events and mortality in subjects with and without known cardiovascular disease." (PMID 24895539, 2014). "The combination of elevated CRP and TNF-α in these non-obese young women coalesces sufficiently that PCOS may link to the development of T2DM and cardiovascular disorder." (PMID 23825680, 2013). "History of cardiovascular disease 1.47 (0.67, 3.26), body mass index(BMI) greater than thirty 0.82 (0.46, 1.41), LDL cholesterol mg/dL 1.0 (0.99, 1.00), smoking 1.18 (0.67, 2.06) and CRP levels (mg/dL), 1.24 (0.90, 1.70) were not independent predictor in this model." (PMID 21569369, 2011). "However, several surrogate markers of cardiovascular disease, including primary outcome cIMT, and carotid score, and secondary outcome cholesterol levels (HDL, non-HDL), triglycerides, C-reactive protein (CRP), and fasting glucose were not affected by metformin." (PMID 33041865, 2020). "Interestingly, a recent publication showed that SAA, but not CRP, has the ability to directly promote vascular proteoglycan synthesis in a pro-atherogenic manner, suggesting that SAA could be a direct link between low-grade inflammation in adipose tissue and cardiovascular disease in obese subjects." (PMID 21611116, 2011).
tumor (1,617 papers, 1980 to 2026). "We identified elevated serum baseline D-Dimer (p = 0.0098) and elevated C-reactive protein (p = 0.0042) concentrations and measurable tumor burden (p = 0.0039) as main risk factors for the occurrence of TEE." (PMID 42041031, 2026). "Biomarkers such as 8-hydroxy-2'-deoxyguanosine, malondialdehyde, F2-isoprostanes, C-reactive protein, interleukin-6, and tumor necrosis factor-α were frequently associated with tumor stage, prognosis, and treatment response." (PMID 41900943, 2026). "Multivariate analysis identified age ≥60 years, upper tumor location, T4 stage, N2-N3 stage, lymphocyte-to-CRP ratio (LCR) ≥ 8,785.7, and geriatric nutritional risk index (GNRI) ≥ 112.9 as independent predictors of overall survival (all p < 0.05)." (PMID 42005437, 2026). "Increased CRP levels, and their association with a larger tumor size, lymph node, or liver metastasis; an advanced Dukes’ stage; and decreased survival, have been demonstrated elsewhere." (PMID 39857073, 2025). "Elevated CRP levels reflect tumor-associated inflammatory responses, often mediated by interleukin-6 and other cytokines, while hypoalbuminemia indicates nutritional compromise, catabolic stress, and chronic systemic inflammation." (PMID 40565984, 2025). "Collectively, these findings establish a theoretical framework for CRP as a broadly applicable tumor-associated inflammatory biomarker while emphasizing the need for prospective validation of its specificity and sensitivity in large-scale, multi-center trials." (PMID 40563367, 2025). "Higher levels of AFP, NLR, AAR, ALBI score, SII, and decreased CALLY index and N/CRP ratio were associated with increased pretreatment total tumor size, advanced BCLC stage, and out-of-UCSF criteria (P < .05)." (PMID 40181742, 2025). "Concurrently, multivariate Cox regression analysis for OS revealed that higher levels of CRP>10 mg/L (p = 0.014) and recurrent tumor (p = 0.028) were independent risk factors, while responder based on RECIST 1.1 (p = 0.006) was independent protective factor." (PMID 40666526, 2025). "Elevated CRP levels have been associated with tumor growth, metastasis, and therapy resistance in multiple malignancies." (PMID 40563651, 2025). "The higher CRP/albumin ratio was associated with tumor progression, high CLIP and BCLC scores, and decreased liver function reserve." (PMID 40181742, 2025). "Elevated CRP levels serve as a direct marker of activation of the IL-6 signaling pathway, which has been implicated in promoting tumor cell survival, proliferation, and chemotherapy resistance." (PMID 41586228, 2025). "Data from patients with lung cancer indicate that D-dimer, CA125, CA199, and CRP are biomarkers associated with this type of neoplasia." (PMID 40584524, 2025). "Consistent with previous analyses, higher levels of pretreatment AFP, NLR, AAR, ALBI score, SII, and decreased CALLY index and N/CRP ratio were associated with the presence of vascular invasion and last tumor size." (PMID 40181742, 2025). "Systemic inflammatory biomarkers, including white blood cell (WBC) count and C-reactive protein (CRP), have emerged as critical indicators of tumor-associated inflammation." (PMID 40832638, 2025). "High levels of CRP, a general marker of systemic inflammation, have been associated with increased tumor burden, lymph node involvement, and reduced overall survival." (PMID 40901118, 2025). "In this review, we evaluate both the established and novel protein–protein interactions (PPIs) for CRP with an emphasis on discerning the network of interactions that underly CRP’s role in modulating tumor development, progression, and treatment resistance." (PMID 41614767, 2025). "This includes identifying the presence of predictive factors for occult neoplasia, such as clinical factors (age, risk factors, and severity) and biomarkers (CRP, D-dimer), as well as neuroimaging findings (RNMC DWI: “three parts”)." (PMID 40584524, 2025).